HSPA1A (heat shock protein family A (Hsp70) member 1A)
Diseases named in the same sentence as HSPA1A in open-access papers (continued):
Sharing a sentence is not in itself a finding about the gene and the disease.
tumor (continued). "Upregulated within the tumor-infiltrating CD4+ T cells were heat shock proteins (HSPA1A and HSPA1B), Jun and FOS constituents (FOS, JUN, and JUNB), MHC-II molecules (HLA-DRB), and secreted molecules (CCL5, GZMA, and GZMK)." (PMID 33504936, 2021). "Collectively, the results suggested that NONHSAT079852.2 acts as a sponge of hsa-mir-10401-3p and thereby enhances HSPA1A expression, promotes tumor cell proliferation and invasion, and leads to the progression and recurrence of GBM." (PMID 34307121, 2021). "The overexpression of HSPA1A, CD99 and RAB3A showed to be associated with advanced tumour stage, tumour type II, tumour progression, and primary chemotherapy resistance." (PMID 33686173, 2021). "HSPA1A protects tumor cells from oxidative stress, inflammatory cytokines, hypoxia, and other stress." (PMID 34765552, 2021). "Searching the literature, we found one study reporting the downregulation of HSPA1A in tumor cells by intravenous administration of IgG, due to high titers of anti-HSPA1A antibodies." (PMID 34769520, 2021). "Heat shock 70 kDa protein 1A (HSPA1A), a major member of the 70 kDa stress protein family, is increased in a variety of tumor types." (PMID 35126454, 2021). "Nowadays, mounting evidence regarded HSPA1A as an important biomarker in tumor progression, metastasis and drug resistance of various cancers." (PMID 34041868, 2021). "In agreement with the RNA‐Seq data, the secretome of tumour cells from 7 different patients contained high levels of HSPA1A after culturing in 50% ascites for 24 h, with MS signals ranking among the top 10 cytokines." (PMID 34841720, 2021). "These mechanistic details will allow us to specifically target the lipid-binding function of HspA1A in order to inhibit the lipid-driven translocation of HspA1A to the cell surface of tumor cells, making them sensitive to radiation therapy." (PMID 32825419, 2020). "Membrane-bound Heat shock protein 70 (Hsp70, Hsp70-1, HspA1A, #3303) has been found to fulfill these criteria, exhibiting a remarkable tumor-specific targeting capability." (PMID 32456049, 2020). "This knowledge provides new information towards elucidating the lipid-driven mechanism of HspA1A’s translocation to the surface of tumor cells." (PMID 32825419, 2020). "For example, binding of HspA1A to intracellular PS or extracellular Gb3 plays a critical role in the localization of HspA1A at the PM of stressed and tumor cells, while binding to extracellularly localized PS regulates cell survival." (PMID 30999671, 2019). "In the case of Gb3, it was established that its interaction with HspA1A enables the protein to localize at the surface of tumor cells as both the lipid’s and the protein’s concentrations increase." (PMID 30999671, 2019). "Heat shock protein 70 (HSP70), also termed HSPA1A, the major stress-inducible member of this family is overexpressed in a large variety of different tumour types." (PMID 29203711, 2018). "The major stress-inducible HSP70, also termed HSPA1A, is frequently overexpressed in a large variety of different tumour types." (PMID 29203711, 2018). "In accordance, when human prostate cell lines overexpressing HSPA1A are injected in mice, there is a significant decrease of tumor growth and increased survival." (PMID 28468249, 2017). "Increased reactivity in NK cells were found together with increased cytolytic activity against HSPA1A-positive tumor targets." (PMID 28468249, 2017). "Along this line, our laboratory investigated the potential of the major stress-inducible heat-shock protein 70 (Hsp70, HSPA1A) as a tumor-specific target." (PMID 26579130, 2015). "Additionally, HSPA1A, a heat shock protein, plays a crucial role in promoting tumor cell survival and chemoresistance, enhancing cancer cell adaptability and stress resistance." (PMID 40891683, 2025). "Furthermore, in vitro assay also showed that the four risk genes (HSPA1A, SEMA4C, CDKN2A, ARHGAP4) were overexpressed in the tumor cells." (PMID 39950044, 2025).
tumor (continued). "To gain a more precise understanding of the expression patterns of IKBKE and HSPA1A in different immune cell and cancer cell subpopulations, as well as their potential roles within the tumor microenvironment, we explored their expression in LIHC using single-cell transcriptomic analysis." (PMID 39000042, 2024). "Furthermore, our q-PCR results revealed a substantial increase in the transcription levels of IKBKE and HSPA1A in LIHC tumor tissues compared to adjacent normal tissues." (PMID 39000042, 2024). "Notably, cluster 4 ECs were scarce in tumor cells but represented an activated EC subset (HSPA1A+) with MHC II-restricted antigen-presenting function, suggesting potential antitumor effects." (PMID 37533434, 2023). "Cluster 1 comprises genes important for skeletal muscle (ACTA1) and muscle function (ACTN1) and includes a crucial gene (AKT1) known to regulate insulin signaling, cell survival, and tumor progression, as well as two chaperones: HSPA1A and HSPB1 (heat shock proteins (HSPs))." (PMID 36767649, 2023). "The concordance of our extracellular findings with these intracellular analyses suggests that determination of HSPA1A levels in the extracellular milieu may be a less invasive method to evaluate these tumor-related variables." (PMID 35906272, 2022). "The HSPA1A level increased proportionally with the histological grade of the tumor (p < 0.001)." (PMID 35906272, 2022). "In addition to its cytosolic pro-survival functions, HSPA1A also localizes and embeds in the plasma membrane (PM) of stressed and tumor cells." (PMID 35740982, 2022). "Tumor NK cells expressed similar DEGs to tumor T cells and were enriched for genes associated with protein folding and cytokine expression, including genes coding for heat shock proteins HSPA6, HSPA1B, and HSPA1A, and IFNG, a common cytotoxic marker." (PMID 35534852, 2022). "Therefore, manipulating HSPA1A’s PM translocation and EM export are promising therapeutics to reduce tumor resistance and improve health outcomes." (PMID 35740982, 2022). "Intracellular HSPA1A can inhibit cell apoptosis and interrupt the senescence process, which are two mechanisms that are central to the prevention of unrestrained cell division and whose inhibition can lead to tumor formation 5,9,31." (PMID 35906272, 2022). "Besides, the high HSPA1A, HSPA1B, HSPA4, HSPA5, HSPA8, HSPA13, and HSPA14 expressions were inversely associated with the overall survival rate of patients, tumor grade, and cancer stage." (PMID 34059060, 2021). "Gabriele Multhoff (Technical University of Munich, Germany) showed that the major stress-inducible Hsp70 (HSPA1A) is frequently overexpressed in the cytosol of a large variety of different tumor entities and presented on the plasma membrane in a tumor-specific manner." (PMID 33559835, 2021). "High level of intracellular HSPA1A can prevent cancer cells from apoptotic cell death, promote cancer cells proliferation or migration, and mediate therapeutic resistance, thus contributing to the formation of aggressive tumor phenotypes." (PMID 35126454, 2021). "The authors proposed that an inverse correlation might exist between HSPA1A expression and autophagy in tumor cells." (PMID 34782665, 2021). "HSPA1A is involved in the promotion of tumor cell proliferation, metastasis, and invasion." (PMID 34765552, 2021). "It has been indicated that HSPA1A plays an important role in tumor development." (PMID 34765552, 2021). "As for HSPA1A, a kind of inducible heat shock protein promotes tumor cell growth and survival." (PMID 33880366, 2021). "In addition to its intracellular anti-apoptotic functions, HspA1A also localizes in the plasma membrane (PM) where it is presented on the surface of many different human tumor types resulting in radiation insensitive and metastatically aggressive tumors." (PMID 32825419, 2020).
tumor (continued). "However, expression levels of DNAJB1 (p = 0.018), HSPB2 (p < 0.001), HSPB6 (p < 0.001) and HSPA1A (p = 0.021) were significantly lower in tumor tissues." (PMID 31222140, 2019). "Membrane-bound HspA1A plays important biological roles, as it activates the immune system, mediates clathrin-independent endocytosis, facilitates viral entry, and regulates tumor cell survival." (PMID 30999671, 2019). "HspA1A also localizes at the plasma membrane (PM) of tumor and stressed cells." (PMID 30999671, 2019). "Examples of anti-tumor activity of secreted HSPs include HSPA1A and HSP90AA1." (PMID 28468249, 2017). "However, other functional consequences of the epigenetic silencing of HSPA1A in cancer should be explored with regard to tumor biology and chemotherapeutic response." (PMID 23874968, 2013). "The prevention of the pro-inflammatory activity of neutrophils, enhanced by OC cells (via expressed HspA1A), may protect against tumor progression and metastases." (PMID 22528050, 2012). "The environment surrounding cancer cells is deficient in oxygen, nutrients, and glucose but is enriched in pro-inflammatory cytokines and cytotoxic agents that enhance the basal level of HspA1A in tumor cells and which, on the other hand, is essential to the growth and survival of cancer cells." (PMID 22528050, 2012). "However, we observed that OC cells from various tumor samples differed in the amount of intracellular HspA1A and values of ODI ranged from 101,896 to 340,623." (PMID 22528050, 2012). "Numerous reports demonstrate that basal levels of HspA1A, both in a serum and in a tumor microenvironment of patients with various cancers (breast, lung, prostate, colorectal, pancreatic), often correlate with poor survival and response to chemotherapy of patients." (PMID 22528050, 2012). "Inducible heat shock protein (HspA1A) promotes tumor cell growth and survival." (PMID 22528050, 2012). "HSPA1A/B also appears to have additional effects on cytotoxic T-lymphocytes (CTL) that do not require the binding of tumor associated antigens to the HSP." (PMID 24213112, 2011). "However, the role of the stress-associated HSP HSPA1A subgroup in the tumor immune modulation process is not clearly defined." (PMID 38994941, 2024). "It is still elusive on how HSPA1A contributes to an aggressive form of tumour, however some studies argue that its high levels in the cell might protect cancer cells from apoptosis, thus promoting tumour cell proliferation and migration." (PMID 33686173, 2021). "The dose-dependent nature of HSPA1A/B levels in response to radiation directly results in maximum release of HSPA1A/B into the serum by 24 hours post-exposure and returned to baseline values by 96 hours in both human xenografts and syngeneic tumor-bearing mice." (PMID 24213112, 2011). "First, our study showed that naïve T-cells in tumor tissues exhibit increased expression of HSPs, including HSPD1, HSPE1, HSPA1A, HSPA6, and DNAJB1." (PMID 41186645, 2026). "We observed slight increases in tumor samples for heat shock proteins (HSP), only significant for HSPA1A." (PMID 40703808, 2025). "Moving forward, we delve into the complex relationship between IKBKE, HSPA1A, and immune infiltration in LIHC, shedding light on the intricate interactions within the tumor microenvironment and paving the way for more targeted therapeutic approaches." (PMID 39000042, 2024). "Afterwards, we delved into the validation of IKBKE and HSPA1A expression in LIHC, elucidating their potential role in the tumor microenvironment of LIHC." (PMID 39000042, 2024). "In essence, our comprehensive correlation analysis underscores the profound connection between IKBKE, HSPA1A, and immune cell infiltration in the LIHC tumor microenvironment." (PMID 39000042, 2024).
tumor (continued). "We are eager to delve deeper into the single-cell expression patterns of IKBKE and HSPA1A in LIHC, with the ultimate goal of unraveling their precise functions within distinct immune cell subpopulations of the tumor microenvironment." (PMID 39000042, 2024). "Compared with normal samples, the expressions of HSPA1A, HSPB1 and SERPINA1 were down-regulated in tumor samples, while TIMP1 was up-regulated in tumor samples." (PMID 39115879, 2024). "By specifically interacting with HSP70 isoforms, including HSPA1A/B and HSPA9, YK5 was identified to exhibit anti-tumor activity." (PMID 37189349, 2023). "In groups A5, A6, A7, and A8, genes such as CXCL13, HSPA1A, CREM, CCL4, and FOS were highly expressed in CD8+ or CD4+ T cells in tumor tissues." (PMID 37762493, 2023). "In contrast, tumor T cells’ DEGs coded for heat shock proteins, such as HSPA6, HSPA1A, and HSPA1B in addition to genes related to T cell development and function, such as NR4A1 and NR4A2." (PMID 35534852, 2022). "The heat-shock genes HSPA1A and HSPA1B show down-regulation in tumor and up-regulation in the periphery, and act as marker genes for neuron clusters." (PMID 35327982, 2022). "Here we demonstrate that ARID2 acts as an important tumor suppressor gene in LUADs and reveal that ARID2 depletion induces HSPA1A expression potentially through a transcriptional de-repression mechanism." (PMID 34858604, 2021). "Given that the majority of Treg_C2_HSPA1A cells was in tumours and originated from Treg_C1_SELL cells according to the pseudotime trajectory analysis, the scarce expression of the resident markers might suggest the most recent recruitment of Treg_C2_HSPA1A cells from peripheral blood." (PMID 33531485, 2021). "The higher HSPA1A, HSPA1B, and HSPA13 expressions were positively correlated with higher cancer stage and tumor grade." (PMID 34059060, 2021). "In this present study, we found that HSPA1A directly binds with LASP1, co‐located in the cell cytoplasm and plays a synergistic role in promoting tumours in HNSCC by elevating the interaction between LASP1 and P‐AKT." (PMID 31793711, 2020). "Five of 6 probes (HIST1H1E, HIST1H4B, HIST1H4E, HIST4H4, 5960086) in the Normal dataset were also present in the analysis using all samples and 2 (HSPA1A, IER5) were in common in Tumor dataset." (PMID 23308215, 2013). "As the most prominent tissue‐resident ILC3 subsets in tumour, ILC3‐HSPA1B is distinguished by upregulated expression of cell stress‐related genes (e.g., HSPA1B, HSPA1A, and JUN), all of which have been reported to be involved in cellular stress responses and adaptive mechanisms." (PMID 41527493, 2026). "The elevated expression of HSPs such as HSPD1, HSPE1, HSPA1A, HSPA6, and DNAJB1 suggests that naïve T-cells in tumor tissues may be under a state of stress or heat shock." (PMID 41186645, 2026). "The 72 kDa heat-shock protein HSP70 (HSPA1A) has been identified on the membrane of various tumour cells, displaying a tumour-specific localisation absent in normal human cells." (PMID 40313865, 2025). "If the same observations follow for cancer cases, a connection between HSPA1A, IQGAP1, and Tsg101 may reveal crucial information on tumor exosome formation and cargo sorting." (PMID 41369326, 2025). "We also observed a downregulation of stress response proteins (HSPA1A/HSPA1B, HSPA5, SERPINH1), suggesting that TSA might affect cellular stress response pathways, potentially impacting tumor cell survival." (PMID 40429900, 2025). "Furthermore, when comparing T cells from BM with those from primary tumor IV, we observed significant alterations in the expression of genes such as PLP1 (log2FC = 2.34), HSPA1A (log2FC = 2.09), HBB (log2FC = −2.93), and HBA2 (log2FC = −2.44)." (PMID 38612588, 2024). "The specific influence of HSPA1A and PPARGC1A on immune B cells implies that these genes might impact the regulatory functions of B cells within the HCC tumor microenvironment." (PMID 37993485, 2023).
tumor (continued). "On the contrary, HSPA1A, SERPINA1 and CXCL1 are highly expressed in tumor tissues." (PMID 37950156, 2023). "In total, five populations were designated tumour clusters, which had various features: (TumourC0) CD74 and APOD; (TumourC1) IF16, JUN and HSPA1A; (TumourC2) S100B and SCRG1; (TumourC3) NEAT1 and MALAT1; and (TumourC4) WFDC2 and RNASE1 (HLA‐DRA, CD68, CD3D, CD3E)." (PMID 37784253, 2023). "The presence of this correlation indicates that HSPA1A and PPARGC1A may be involved in creating an immunosuppressive microenvironment favorable for tumor growth and progression." (PMID 37993485, 2023). "This suggests that the expression levels of HSPA1A and PPARGC1A might have a specific impact on the behavior and function of immune B cells in the tumor microenvironment of HCC." (PMID 37993485, 2023). "By modulating the behavior of B cells, HSPA1A and PPARGC1A might affect the antigen presentation process, influencing the activation and function of tumor-specific T cells." (PMID 37993485, 2023). "While intracellular HSPA1A levels in tumor tissues were not evaluated in our study, it is well known that extracellular HSPA1A levels reflect elevated intracellular concentrations." (PMID 35906272, 2022). "Notably, HSP70 (including HSPA1A and HSPA1AB), a ubiquitous molecular chaperone, was highly expressed in tumor-derived NK cells." (PMID 35967424, 2022). "The tumor-promoting effect of NONHSAT079852.2 may be attributed to its competitive binding to hsa-mir-10401-3p, and the resulting bond upregulates HSPA1A expression." (PMID 34307121, 2021). "Hspa1a knockdown dramatically decreased tumor burden and number in KA mice without significant impact upon K mice." (PMID 34858604, 2021). "Finally the third network shows the link among the tumor suppressive microRNA, miR-145, KLF4, p65, and the Heat Shock 70 kDa Protein (HspA1A)." (PMID 26880947, 2016). "On the other hand, HspA1A is highly expressed on the cell surface of tumor cells, but not on normal cells, as an integral membrane-bound protein that can be uniquely identified by cmHsp70.1 monoclonal antibody." (PMID 22528050, 2012). "Indeed, inducible members of the HSP gene family, namely heat shock 70 kDa protein 6 (HSPA6) followed in rank by HSPA1A and HSPA1B were the most dominantly induced genes 4 h after PDT in the human tumor cell lines." (PMID 21738796, 2011). "HSPA1A/B appear to play a role in other aspects of non-specific immune responses: HSPA1A/B is found on the cell surface of some tumor cells and is a target of lymphoid activated killer (LAK) cells." (PMID 24213112, 2011). "The high positive correlation between the expression of HSPA1A and PPARGC1A genes and the infiltration of nTreg cells, B cells, macrophages, and monocytes in TCGA-LIHC suggests a potential role for these genes in regulating immune cell infiltration within the tumor microenvironment of HCC." (PMID 37993485, 2023). "Although currently mere speculation, a possible explanation is that HSPA1A does not depend on a single lipid to go to the PM, and PS externalization might promote HSPA1A’s PM localization as it has been suggested for pre-apoptotic tumor cells." (PMID 35740982, 2022). "In line with a potentially more “silenced” phenotype, these nonlesional tumor cells harbored elevated levels of CXCR4, CD69, HSPA1A, ZFP36, IL7R and TXNIP when compared to matched lesional skin." (PMID 34583709, 2021).